DCK (deoxycytidine kinase)
Diseases named in the same sentence as DCK in open-access papers (continued):
Sharing a sentence is not in itself a finding about the gene and the disease.
cancer (continued). "On the other hand, MDR variants in two cell lines of small cell lung cancer showed increased DCK activity, and human cancer cell lines overexpressing ABCB1 or ABCC1 showed increased sensitivity to gemcitabine." (PMID 35582220, 2020). "Further formulation development will increase the safety and efficacy of these prodrugs to overcome the cancer chemoresistance induced by the down-regulation of DCK." (PMID 35582220, 2020). "As expected, dCK expression was inversely associated with DDB1 expression (p = 0.013), further indicating that dCK was the effector of DDB1 in cancer cell GEM resistance." (PMID 31842285, 2019). "For most of the nucleoside analogues commonly used for anti-cancer therapy, the first phosphorylation step is catalysed by deoxycytidine kinase (dCK)." (PMID 29695239, 2018). "dCK can also activate many antiviral and anti‐cancer nucleoside analogs, such as fludarabine, gemcitabine, cladribine and zalcitabine." (PMID 29701272, 2018). "An integrative structural and chemical biology program identified dCK as the target protein responsible for the masitinib sensitisation effect on gemcitabine-refractory cancer cells." (PMID 29127277, 2017). "Many of the cell lines included in the Cancer Cell Line Encyclopedia7, 8 express dCK at higher levels than the corresponding normal tissues." (PMID 28808226, 2017). "In the present work, we identified deoxycytidine kinase (dCK) as the target responsible for the sensitisation of various cancer cell lines to gemcitabine, using reverse-proteomics." (PMID 29127277, 2017). "The dCK is also involved in the activation of other compounds, that are structurally related to deoxycytidine and are used as anti-cancer or anti-viral drugs." (PMID 26485161, 2015). "The ability of M36 to strongly sensitise cells to two of the drugs that are routinely employed in the treatment of different types of cancer with poor prognoses makes this dCK mutant a particularly promising candidate for suicide gene approaches." (PMID 26485161, 2015). "The dCK enzyme is paramount in the deoxynucleoside salvage pathway and in the activation of numerous nucleoside analogues used in cancer and in antiviral chemotherapy including 2-CdA." (PMID 25937997, 2014). "dCK is a promising target for cancer treatment and PET probes targeting dCK activity will be useful in predicting and following clinical response to such therapy." (PMID 25101980, 2014). "As a result, the tissue distribution and relative expression levels of dCK in normal and cancer cells can influence both therapeutic efficacy and toxicity of clofarabine and other nucleoside analogs phosphorylated by dCK." (PMID 24066967, 2013). "This will be followed by discussions of recent advances in our understanding of dCK activation via post-translational modifications in response to radiation and current strategies aimed at enhancing this activity in cancer cells." (PMID 24066967, 2013). "The 5-Aza-2-dC is a pro-drug that requires metabolic activation by deoxycytidine kinase to exert its function as anti-cancer drug." (PMID 21373641, 2011). "Therefore, dCK inhibitors are potentially a high-priority companion therapy for PARP inhibitors for this genetically-defined cancer type." (PMID 40519286, 2025). "Moreover, enrichment of oxidative phosphorylation (OXPHOS)-associated genes was a common property shared by PDAC cell lines, and patient clinical samples coupled with low DCK expression was also demonstrated, which implicates DCK in cancer metabolism." (PMID 38346958, 2024). "In gemcitabine-induced myelosuppression mice, DGBX decoction enhances the anti-cancer effect of gemcitabine by regulating the expression of stress response protein Hu antigen R (HuR), deoxycytidine kinase (dCK), and nuclear factor erythroid 2-related factor (Nrf2)." (PMID 39210410, 2024).
cancer (continued). "Subsequently, it was thought that the combination of the newly designed dCK inhibitors with an RNR inhibitor could efficiently fight cancer cells and prevent escape mechanisms, as both pathways (the DNP and SP) would be simultaneously inhibited." (PMID 37248212, 2023). "Indeed, these diseases have shown increased dCK expression relative to normal tissues, as revealed by the RNASeq and quantitative proteomics data of a large panel of human cancer models in the Cancer Cell Line Encyclopedia13 and the Human Protein Atlas14." (PMID 37248212, 2023). "Increased DCK expression found in several cancers, including poor prognosis BC, indicates that these patients might be susceptible to treatment with nucleoside analogs." (PMID 36278182, 2022). "DCK is relevant to drug resistance in cancer, but researchers have paid little attention to it." (PMID 36292719, 2022). "The function of DCK in other cancer types should be investigated in the future." (PMID 32690026, 2020). "DCK activity has been reported to correlate with gemcitabine sensitivity in cancer cells." (PMID 33287390, 2020). "The DCK gene is inactivated in all of the seven obtained gemcitabine-resistant cancer cell lines." (PMID 35582220, 2020). "Importantly, dCK is a pyrimidine metabolism enzyme essential to the activity of several anti-cancer pro-drugs such as gemcitabine and decitabine." (PMID 31703407, 2019). "Thus, hENT1, hCNT1, hCNT3, and dCK positively contribute to gemcitabine activity and to cancer cells' sensitivity to gemcitabine." (PMID 28327155, 2017). "Thereby, the possibility of foreseeing gene therapy approaches based on the insertion of extra copies of the dCK gene in cancer cells appears promising and the possibility of generating variants of dCK with improved dCa phosphorylation activity is a major goal in the field." (PMID 26485161, 2015). "DCK catalyzes the first phosphorylation (=activation necessary for their cytotoxic activity) not only of araC into araCMP, but also of most nucleoside analogs (both pyrimidine and purine-derived) commonly used in anti-cancer therapy." (PMID 24972933, 2014). "In principle, blockade of dCK by a small molecule inhibitor may sensitize cancer to a wide range of genotoxic agents, including IR." (PMID 25101980, 2014). "However, many cancers resist to GEM and the main involved mechanism consists of an up-regulation of the catabolic enzyme Cytidine Deaminase (CDA), deficiency in the anabolism enzyme Deoxycytidine Kinase (DCK), and alterations in nucleoside influx transporters." (PMID 36059648, 2022). "Deoxycytidine kinase (dCK) is a rate-limiting enzyme in the deoxyribonucleoside salvage pathway which is expressed predominantly in rapidly proliferating cells, including hematopoietic progenitors in thymus and bone marrow, activated lymphocytes, and cancer cells." (PMID 24733693, 2014). "Expression analysis of the key enzymes that regulate gemcitabine uptake (hENT1) and intracellular metabolism (CDA, DCK, NT5C1A, and DCTD) was performed in cancer cells and PSCs by immunofluorescence and by western blot analysis using total cell lysates." (PMID 33287390, 2020). "Immunohistochemical analysis of the source tumors revealed strong positive staining for hENT1, CDA, DCK, and NT5C1A in the cancer cells, whereas minimal expression was detected in the stromal cells." (PMID 33287390, 2020). "Deoxycytidine kinase (DCK) is an enzyme, which metabolizes several anti-cancer chemotherapeutic agents including gemcitabine." (PMID 23965981, 2013). "This approach may also benefit other types of cancer where the methylation of genes such as SLC29A1 and DCK is pivotal for the uptake and activation of nucleoside analogs." (PMID 40723396, 2025). "In contrast, although ATRi reduces RRM1 and RRM2 protein in cancer cells, it does not reduce dCK protein in cancer cell lines." (PMID 36130512, 2022).
cancer (continued). "Two previously established CNDAC-adapted cancer cell lines had been shown to display reduced DCK levels but a contribution of SAMHD1 had not been investigated." (PMID 34641952, 2021). "Similarly, among AML sublines adapted to a range of different anti-cancer drugs, only nucleoside analogues that displayed increased SAMHD1 and/ or decreased DCK levels were less sensitive to CNDAC." (PMID 34641952, 2021). "It is believed that Ara-C enters cancer cells via the human equilibrative nucleoside transporter 1 (hENT1), and is subsequently phosphorylated to cytarabine-triphosphate (Ara-CTP) by deoxy-cytidine kinase (dCK)." (PMID 27462781, 2016). "The ability of cancer cells to switch from pyrimidine de novo synthesis via RNR to pyrimidine salvage, to maintain efficient DNA synthesis, and to escape allosteric RNR inhibition with dT resulted in the development of a strategy to co-target RNR and the pyrimidine salvage enzyme dCK." (PMID 35203388, 2022). "In cancer cells, gemcitabine-induced cytotoxicity was significantly lower following knockdown of hENT1 and DCK, whereas knockdown of CDA and NT5C1A had no impact, highlighting the importance of a balanced expression of the key regulators of gemcitabine metabolism for treatment effects to occur." (PMID 33287390, 2020). "Furthermore, the key gemcitabine regulators hENT1, DCK, CDA, and NT5C1A were expressed to varying degrees among the different cancer cells, whereas PSCs displayed overall significantly lower expression than the cancer cells." (PMID 33287390, 2020). "Since competition for the dCK enzyme between natural substrate and incoming drug molecules is crucial for the efficiency of cell death induction, this feature suggested that such mutants once introduced into cancer cells would not have induced a sensitisation to the treatment." (PMID 26485161, 2015). "We also hypothesized that the absence of dCK will increase cancer radiosensitivity." (PMID 25101980, 2014).
bacterial infection (2 papers, 2024). "Thus, (R)-DI-87-mediated inhibition of dCK may also help to protect host cells from apoptotic cell death or other adverse effects during other bacterial diseases in human or animal hosts." (PMID 38512723, 2024). "Inventor in a patent application covering the use of dCK inhibitors as a treatment for bacterial infectious diseases (patent pending, No. 63/450,304 USPTO)." (PMID 38512723, 2024).
infection (2 papers, 2024 to 2025). The state of being infected such as from the introduction of a foreign agent such as serum, vaccine, antigenic substance or organism. "Following infection, the expression of the DCK gene was markedly upregulated." (PMID 40141146, 2025). "Moreover, infection with S. aureus adsA-deficient bacteria phenocopied (R)-DI-87-mediated inhibition of dCK, in line with the concept that AdsA is required for establishing persistent infections in host tissues." (PMID 38512723, 2024). "Thus, inhibition of host dCK represents an attractive host-directed therapeutic intervention strategy that terminates a refined immuno-evasive maneuver S. aureus has evolved to establish persistent infections in mammalian hosts." (PMID 38512723, 2024).
infectious disease (1 paper, 2024). A disorder directly resulting from the presence and activity of a microbial, viral, or parasitic agent in humans. "Thus, pharmaceutical blockade of dCK represents an advanced anti-infective intervention strategy against which staphylococci cannot develop resistance and may help to fight fatal infectious diseases in hospitalized patients." (PMID 38512723, 2024).
DCK also shares sentences with these, for which no sentence is quoted: biliary tract cancer (2 papers); blood cancers (1); chronic lymphocytic leukemia (1); chronic obstructive pulmonary disease (1); co-infection (1); esophageal tumours (1); gastric cancer (1); glioblastoma (1); hematological malignancies (1); hyperinsulinemic hypoglycemia (1); idiopathic pulmonary fibrosis (1); liver cancer (1); mantle cell lymphoma (1); metastatic disease (1); mucinous adenocarcinoma (1); multiple myeloma (1); myelodysplastic syndrome (1); Myeloid Malignancies (1); osteosarcoma (1); pancreatic cystadenoma (1); pancreatic ductal adenocarcinoma (1); pancreatic tumour (1); papillary adenoma (1); triple-negative breast carcinoma (1); viral infection (1).